RELA (RELA proto-oncogene, NF-kB subunit)
Diseases named in the same sentence as RELA in open-access papers (continued):
Sharing a sentence is not in itself a finding about the gene and the disease.
osteoporosis (11 papers, 2017 to 2026). A condition of reduced bone mass, with decreased cortical thickness and a decrease in the number and size of the trabeculae of cancellous bone (but normal chemical composition), resulting in increased fracture incidence. "Therefore, NF-κB1 and RELA gene were significantly associated with bone response to the treatment of zoledronic in postmenopausal Chinese women with osteoporosis." (PMID 36011257, 2022). "NFKB1, IL-1β, and RelA had an increased binding potency which mainly explains Quercetin’s anti-osteoporosis activity." (PMID 36839278, 2023). "In our study, we chose 13 SNPs in the NF-κB1 gene, NF-κB2 gene, RELA gene, RELB gene and REL gene of the NF-κB pathway to investigate the association between the NF-κB pathway variations and bone response to zoledronic acid therapy in Chinese postmenopausal women with osteoporosis or osteopenia." (PMID 36011257, 2022). "In addition, genetic reduction in the level of the NF‐κB subunit p65/RelA in Ercc1−/∆ mice, with a lifespan 6 months, delayed the onset of age‐related pathology including osteoporosis, neurodegeneration, BM hypoplasia, epidermal atrophy, sarcopenia, liver and kidney dysfunction." (PMID 28229533, 2017). "In conclusion, this study revealed that the NF-κB signaling pathway, including the NF-κB1 RELA and NLRC5, may be implicated in alendronate's success in the treatment of osteoporosis, which can provide an early prediction of alendronate's efficacy in the treatment of osteoporosis." (PMID 35368772, 2022). "Therefore, the IL1B and NF-κB (RelA and NFKB1) signaling pathways are key targets to treat osteoporosis phenotypes." (PMID 35888070, 2022). "Furthermore, bioinformatics analysis revealed that RELA, NFKBIA, and IKBKB, which all belong to the NF-κB family, were hub genes shared between ICA-targeted genes and osteoporosis." (PMID 34803690, 2021).
diabetes (10 papers, 2013 to 2024). "Diabetes is associated with glucose-induced upregulation of pro-inflammatory and pro-apoptotic markers, including RelA (NF-kB) and IKK." (PMID 38983568, 2022). "In age-at-onset and diabetes duration adjusted models, RELA/11q13 and FCRL3/1q23 SNPs were associated with IA-2A positivity, LPP/3q28 SNPs were associated with GADA positivity, and IFIH1/2q24 was associated with positivity for autoantibodies related to autoimmune gastritis and thyroid disease." (PMID 36181724, 2022). "Therefore, the inhibition of AKT and RELA signaling is critical for the improvement of pathophysiological conditions including cancer, neuroinflammation, and diabetes." (PMID 38003461, 2023). "RELA, JUN, and PTGS2 mediate inflammatory pathways that ultimately drive insulin resistance, diabetes, and its complications." (PMID 39458839, 2024). "Similar results were also shown in diabetes models in which SETD7 interacts with RelA, facilitating the nuclear translocation of RelA and promoted function of NF-κB to transactivate downstream genes." (PMID 35812730, 2022).
liver fibrosis (10 papers, 2012 to 2025). "Phosphorylation of the RelA subunit at serine 536 (RelA-P-Ser536) is important for hepatic myofibroblast survival and is mechanistically implicated in liver fibrosis." (PMID 22996371, 2013). "The findings in this study provide deeper insights into the role of acetylation of RELA in regulating liver inflammation and fibrosis, which improves our knowledge on the prevention of liver fibrosis in humans from the perspective of PTMs." (PMID 41322258, 2025). "In the present study, we demonstrate that total protein and RELA acetylation are significantly decreased in liver fibrosis and acute liver inflammation in vivo, and in primary hepatocytes stimulated by LPS." (PMID 41322258, 2025). "Post-translational modifications (PTMs) regulate the activity and functionality of RELA, but their role in the pathogenesis of liver fibrosis is unclear." (PMID 41322258, 2025). "have reported that RELA is required for fibrous formation in mice with chronic pancreatitis and that inhibition of RELA significantly reduced liver fibrosis." (PMID 35166167, 2022). "However, the mechanism through which RELA protein modifications regulate liver fibrosis remains incompletely understood." (PMID 41322258, 2025). "At present, how the acetylation of RELA regulates the pathogenesis of liver fibrosis is still unknown, even in mammals." (PMID 41322258, 2025). "Meanwhile, RelA expression may protect against liver fibrosis and hepatocellular damage, and the expression of RelA is inversely correlated with liver cell apoptosis and with the rate of fibrosis progression." (PMID 35330838, 2022). "The RelA/NF-κB/caspase signaling pathway may play a pivotal role in regulating the inflammation pathway in TAA-induced liver fibrosis." (PMID 33817258, 2020). "Given the potent effects of SIRT7 inhibitor on suppression of LPS-mediated liver inflammation, we examined whether SIRT7 inhibitor could exert a similar role in suppressing liver fibrosis in a fish model induced by chronic inflammation preventing RELA deacetylation." (PMID 41322258, 2025). "This study was performed to understand the regulation mechanism of acetylation of RELA on liver inflammation and fibrosis in a model animal of innate glucose intolerance, largemouth bass, and to provide a potential target and biomarker for liver fibrosis therapy." (PMID 41322258, 2025). "Thus, we found that the levels of NAD + were significantly enhanced in fibrotic livers, further supporting the notion that sirtuin family members (SIRT1-7) may play important roles as crucial regulators of liver fibrosis and the deacetylation of RELA." (PMID 41322258, 2025). "In addition to RelA subunit, c-Rel is also reported to play a role in liver fibrosis development." (PMID 33671028, 2021). "Subsequently, we examined whether the favorable effects on mitigating liver fibrosis and liver inflammation mediated by SIRT7 inhibition is through its influence on the acetylation of RELA." (PMID 41322258, 2025). "Our study has revealed a previously unrecognized molecular link between the deacetylation of RELA and its transcription activity, and expression of target genes by SIRT7, which further regulates the liver inflammation and the development of liver fibrosis in largemouth bass." (PMID 41322258, 2025).
liver fibrosis (continued). "We propose a model in which stress promotes RELA nuclear translocation to facilitate the interaction with SIRT7, leading to enhanced RELA deacetylation and the subsequent aggravation of liver inflammation and the development of liver fibrosis." (PMID 41322258, 2025). "The results revealed that quercetin and luteolin could activate the PI3K-Akt signaling pathway and inhibit liver fibrosis by binding to hub targets, including AKT1, CCND1, EGFR, MAPK1, MYC, and RELA." (PMID 37083803, 2023).
asthma (9 papers, 2017 to 2026). "Further, rs932476 in PLA2G4A and rs931127 in RELA were also marginally associated with asthma (p = 0.0036 and p = 0.035, respectively)." (PMID 27504716, 2017). "This study identified interactions between genetic variants near or within five genes, PLA2G4A, PLA2R1, RELA, PRKD1 and PRKCA, and occupational exposures to LMW agents or irritants for current adult-onset asthma." (PMID 27504716, 2017). "Overall, all these data suggest that any or all of these genes—PLA2G4A, PLA2R1, RELA, PRKD1, and PRKCA—may play a role in the risk of asthma in adults in association with exposure to LMW agents or irritants." (PMID 27504716, 2017).
psoriasis (9 papers, 2012 to 2025). An autoimmune condition characterized by red, well-delineated plaques with silvery scales that are usually on the extensor surfaces and scalp. "Among the key target genes, MAPK3 and RELA were connected to all four psoriasis-related pathways, highlighting their critical role in the therapeutic mechanism of SHTLS." (PMID 40507893, 2025). "Sequential biopsies obtained from psoriasis patients undergoing treatment with etanercept, a TNF antagonist used for psoriasis therapy, demonstrated a significant reduction in phosphorylated NF-kB/RelA." (PMID 38203337, 2023). "Secondly, RELA, MAPKs, JUN, and BCL2L1 are associated with the aberrant biological behaviours of keratinocytes in psoriasis." (PMID 32655662, 2020). "Then we confirmed that the expression of RelA/p65 was elevated in lesions and PBMCs of psoriasis patients, which was in accordance with other previous studies." (PMID 27708240, 2016). "Components of the NFκB pathway have been shown to be active in psoriasis, and NFκB and RELA TFs were both activated." (PMID 22957057, 2012). "Constitutively active NF-κB/RelA is present in uninvolved epidermis from psoriasis patients, and etanercept treatment significantly downregulates phosphorylated NF-κB/RelA correlating with the restoration of normal markers of keratinocyte differentiation and clinical outcome." (PMID 35740272, 2022). "qRT-PCR analyses found that both NRIP1 and RelA/p65 were elevated in psoriatic lesions compared to psoriatic non-lesions and normal controls, and also overexpressed in peripheral blood mononuclear cell (PBMCs) of psoriasis patients." (PMID 27708240, 2016). "In conclusion, our data suggests that NRIP1 is overexpressed both in skin and PBMCs of psoriasis patients and may be involved in the abnormal proliferation and apoptosis of keratinocytes, as well as the immune reaction through the regulation of RelA/p65." (PMID 27708240, 2016). "A recent study revealed that NRIP1 may stimulate the activity of NF-κB by forming a trimeric complex with RelA and CBP, and upregulate downstream inflammatory genes, including TNF-α and IL-6, both of which play crucial roles in the pathogenesis of psoriasis." (PMID 27708240, 2016).
rheumatoid arthritis (9 papers, 2015 to 2026). A chronic, systemic autoimmune disorder characterized by inflammation in the synovial membranes and articular surfaces. "Here, we identify ALOX5 as a previously unrecognized direct target of celastrol and further demonstrate that the ALOX5–macrophage axis drives bone destruction in rheumatoid arthritis through a novel transcriptional mechanism involving NF-κB/RELA." (PMID 41408107, 2025). "RESULTS: Integrated analysis identified 34 common targets of Er Miao San (EMS) for rheumatoid arthritis (RA) treatment, with NFKBIA, RELA, and TNF recognized as the top hub genes." (PMID 41963877, 2026). "Although the underlying mechanism is elusive, our ChIPEA suggested that LEF suppresses tumor growth by activating TLE3 and inactivating RELA and E2F1, possibly via the same mechanisms involved in rheumatoid arthritis treatment." (PMID 35073843, 2022).
schizophrenia (9 papers, 2011 to 2025). A major psychotic disorder characterized by abnormalities in the perception or expression of reality. "RELA, which was a common upstream factor of cluster 1 in this study, was reported to be associated with the pathology of schizophrenia." (PMID 33815179, 2021). "In a Japanese population, schizophrenia is associated with variants of the RELA gene and has a significant effect on pre-pulse inhibition." (PMID 34831151, 2021). "Furthermore, several SNP variants of RELA were associated with deficits in pre-pulse inhibition, which is a typical intermediate phenotype of schizophrenia." (PMID 33815179, 2021). "The RELA gene is located on chromosome 11q13, which is suggested to be linked to schizophrenia." (PMID 33815179, 2021). "NF-kappa is also found to be related with schizophrenia since the genetic variants in RELA gene, which encoded the protein RelA as one subunit of NF-kappa B, were reported to be associated with schizophrenia and the patients startle responses in a Japanese population." (PMID 22479419, 2012). "However, gender differences have been reported in the association between schizophrenia and RELA gene encoding the major component of NF-κB, which is activated by IL-1β." (PMID 21843369, 2011). "RELA gene expression was also known to be downregulated in the postmortem tissue of STG in schizophrenia, as observed in its protein and gene expression levels." (PMID 33815179, 2021). "Several studies reported the association between PPI in schizophrenia and HT2AR, COMT, NRG1 and RELA, which also directly or indirectly influence glutamatergic signaling." (PMID 25768306, 2015). "This perhaps explains the greater magnitude of increase in NF-κB2 mRNA found when all people with schizophrenia are grouped together as compared to RelA and NF-κB1 mRNA increases that would be less, on average, considering that non-inflamed people with schizophrenia make about 60% of the cases." (PMID 34650030, 2021). "This suggests that in the chronic phase of schizophrenia, mRNA expressions of inflammatory mediators belonging to cluster 1 may be suppressed by the regulation of upstream transcription factors such as BCL6, RELA, and IRF9." (PMID 33815179, 2021). "Taken together, these findings suggest that NF-κB activation (at least through the canonical pathway that activates the RelA/NF-κB1 heterodimer) may actually be blunted in people with schizophrenia compared to people without schizophrenia who have brain inflammation." (PMID 34650030, 2021).
Sepsis (9 papers, 2015 to 2024). Sepsis is defined as life-threatening organ dysfunction caused by a dysregulated host response to infection. "In sepsis, RELA, CEBPB, NFKBIA, STAT6, IRF8 and SPI1 were downregulated, with no significant change in NFKB1, JUN and GLI1." (PMID 39444551, 2024). "AopP hinders the NF-κB signaling pathway by restraining the transportation of the p50/p65 protein complex (NFKB1/RelA) into the target cell’s nucleus, resulting in the septicemia and furuncles formation (subcutaneous wounds) in host tissue." (PMID 36363710, 2022). "Genes that participate in this pathway and were differentially expressed in our sepsis patients include PSMB1, NFKB2, SEM1, UBB and RELA." (PMID 37731199, 2023). "We then selected four SNPs (NFKB1 rs28362491 ins/delATTG, rs4648068 A/G, RELA rs7119750 C/T, and REL rs842647 G/A) from the canonical pathway of NF-κB and investigated their clinical relevance in relation to the development of sepsis and MODS." (PMID 25880845, 2015). "In the early stages of toll-like receptor 4- (TLR4-) mediated sepsis, SIRT1 rapidly accumulated at TNF-α and IL-1β promoter regions and deacetylated the RelA/p65 lysine 310 site and nuclear histone H4 lysine 16 sites, ultimately promoting NF-κB transcription termination." (PMID 30533222, 2018). "Indeed, our results in RSV-infected mice and previous work in model of experimental sepsis demonstrate greater nuclear translocation of RelA in the lung in absence of Nrf2." (PMID 29740449, 2018).
Alzheimer disease (8 papers, 2011 to 2024). A progressive, neurodegenerative disease characterized by loss of function and death of nerve cells in several areas of the brain leading to loss of cognitive function such as memory and language. "The hub gene, PTSG2, is related to the NF-κB and Alzheimer’s disease pathways, whereas RELA and BCL2 are associated with the NF-κB pathway." (PMID 37719850, 2023). "RELA expression level was closely associated with Alzheimer’s disease, JAK-STAT, MAPK, and chemokine signaling pathways." (PMID 36159817, 2022). "Secondly, the pathology of AD is often accompanied by an inflammatory response, and RELA (P65), an important signaling factor in the NF-κB pathway, is usually involved in the regulation of neuroinflammation to mediate the development and progress of Alzheimer's disease." (PMID 34992508, 2021). "These targets were found to be related to metabolite interconversion enzymes, modified residues, regulation of apoptotic signaling pathway, “Alzheimer’s Disease, Focal Onset”, NFKB1, SP1, and RELA, hsa-miR-17-5p, hsa-miR-16-5p, and hsa-miR-26b-5p." (PMID 39493676, 2024). "“Acute Confusional Senile Dementia”, “Alzheimer’s Disease, Focal Onset”, NFKB1, SP1, and RELA were found to be the most important diseases and transcription factors." (PMID 39493676, 2024). "It was noteworthy that the expression levels of RELA and HSP90AA1 were enriched in Alzheimer’s disease pathways, suggesting their potential important roles in the AD process." (PMID 36159817, 2022). "RELA is involved in TCR-, BCR-, TLR-, and RIG-I-like receptor-signalling pathways, whereas APP is involved in Alzheimer’s disease pathway." (PMID 31666081, 2019).
head and neck squamous cell carcinoma (8 papers, 2008 to 2026). A squamous cell carcinoma that arises from any of the following anatomic sites: lip and oral cavity, nasal cavity, paranasal sinuses, pharynx, larynx, and salivary glands. "In addition, a more recent study of head and neck squamous cell carcinoma proposed a combined effect of both IKKα and IKKβ on the nuclear localization of canonical RelA and alternative RelB and P100/P52 subunits." (PMID 26147201, 2015). "Many tumours, such as head and neck squamous cell carcinoma (HNSCC), exhibit resistance due to activation of the canonical IKK–NF‐κB/RELA pathway." (PMID 41537447, 2026).
Hyperglycemia (8 papers, 2015 to 2024). An increased concentration of glucose in the blood. "Hyperglycemia causes apoptosis of dermal fibroblasts, reduces collagen expression, and upregulates RELA/p65 expression, which implicates the onset of pro-inflammatory and pro-degradative profiles." (PMID 37373317, 2023). "In these studies, the hyperglycemia-induced upregulation of prolyl-isomerase (Pin1) gene expression was functionally associated with nuclear translocation of RelA/p65/NF-kB3 and subsequent enhanced ICAM-1 production." (PMID 27084094, 2016). "RGC death in DR is activated by hyperglycemia-induced O-GlcNAc modification of nuclear factor kappa B (NF-κB) p65 (RelA)." (PMID 36005597, 2022). "We previously reported a strong upregulation of RelA and GFAP in retina after 4-weeks of hyperglycemia." (PMID 38983568, 2022). "It indicates that only women with prior GDM, characterized by hyperglycemia and impaired insulin secretion in our study, exhibited unique IL13 and RELA overexpression profiles." (PMID 36499008, 2022). "In this study, hyperglycemia-induced cone-specific expression of NF-κB family members, including REL, RELA, and NFKB2." (PMID 34434927, 2021).